CITED4 (Cbp/p300 interacting transactivator with ED-rich tail 4)
Description:
Acts as a transcriptional coactivator for TFAP2/AP-2. Enhances estrogen-dependent transactivation mediated by estrogen receptors. May function as an inhibitor of transactivation by HIF1A by disrupting HIF1A interaction with CREBBP. May be involved in regulation of gene expression during development and differentiation of blood cells, endothelial cells and mammary epithelial cells.
Tractability: No criterion of Open Targets' tractability assessment is met for any kind of drug.
Gene: Protein-coding gene on chromosome 1 (40,861,054 to 40,862,363, reverse strand). Ensembl gene ENSG00000179862.
Subcellular location: Nucleus; Cytoplasm
Subcellular location (Human Protein Atlas): Vesicles
Pathways (Reactome):
Gene expression (Transcription): Activation of the TFAP2 (AP-2) family of transcription factors
Gene Ontology:
Molecular function: transcription coactivator activity
Biological process: response to estrogen; positive regulation of DNA-templated transcription; regulation of DNA-templated transcription
Cellular component: cytoplasm; nucleus; nucleoplasm
Genetic constraint (gnomAD): Loss-of-function variants: 3 observed, 1.07 expected, observed/expected ratio (o/e) 2.79. That is too few expected variants to judge how well the gene tolerates losing a copy. Missense variants: 333 observed, 171.07 expected, observed/expected ratio (o/e) 1.95, 90% interval 1.76 to 1.99. Synonymous variants: 167 observed, 84.24 expected, observed/expected ratio (o/e) 1.98, 90% interval 1.71 to 1.99.
Homologues: Orthologues: chimpanzee CITED4 (98% identical), macaque CITED4 (96% identical), dog CITED4 (85% identical), guinea pig CITED4 (84% identical), rabbit CITED4 (83% identical), mouse Cited4 (78% identical), rat Cited4 (76% identical), zebrafish cited4a (38% identical), zebrafish cited4b (34% identical), tropical clawed frog cited4 (28% identical). Paralogues in human: CITED2 (28% identical), CITED1 (27% identical).
Diseases named in the same sentence as CITED4 in open-access papers:
CITED4 is named in the same sentence as 22 diseases in open-access papers, as found by Europe PMC text mining. Sharing a sentence is not in itself a finding about the gene and the disease. The quoted sentences say what the papers report.
cardiac hypertrophy (8 papers, 2019 to 2025). "Next, we sought to determine the switch in molecular mechanisms underlying AKIP1-induced physiological cardiac hypertrophy, focused on the Akt-C/EBPβ-CITED4 pathway." (PMID 36899057, 2023). "On the other hand, CITED4 is a key regulator of exercise-induced physiological cardiac hypertrophy and cardiomyocyte proliferation in mice." (PMID 41295244, 2025). "Another important transcription factor involved in cardiomyocyte proliferation is CITED4, which plays a critical role in exercise-induced cardiac hypertrophy." (PMID 40136658, 2025). "The subsequent activation of CITED4 leads to the phosphorylation of mTOR, a key regulator of cell growth, thereby promoting exercise-induced cardiomyocyte proliferation and cardiac hypertrophy." (PMID 40136658, 2025). "Akt can inhibit the eukaryotic translation initiation factor 4E-binding protein 1(4E-BP1) and upregulate the CBP/p300- interacting transactivator with ED-richcarboxy-terminal domain 4 (CITED4) to enhance cardiac hypertrophy." (PMID 36834623, 2023). "CITED4 overexpression in cardiomyocytes was recently shown to be sufficient for the induction of cardiac hypertrophy and reduction of autophagy, reduced adverse cardiac remodeling, and reduced fibrosis after ischemic injury." (PMID 30765322, 2019). "Cited4 is not essential for mouse embryo development, but in adult rodent hearts, its expression is linked to physiological cardiac hypertrophy induced by exercise training." (PMID 41295244, 2025). "Moreover, p-Akt upregulated CITED4 to promote myocardial hypertrophy by promoting the expression of GATA4." (PMID 36834623, 2023). "Remarkably, an efficient gene delivery of CITED4 by AAV9-based viral vector in wild-type mice was successful and showed an increase in CITED4 levels in the heart, resulting in beneficial physiological heart hypertrophy without adverse effects." (PMID 41295244, 2025). "Physiological cardiac hypertrophy can develop in response to physiological stimuli such as exercise and pregnancy, and entails beneficial cardiac growth often mediated by the IGF1-Akt-C/EBPβ-CITED4 pathway." (PMID 37914850, 2023).
colorectal cancer (3 papers, 2016 to 2025). A primary or metastatic malignant neoplasm that affects the colon or rectum. "Recent studies have sought to elucidate the role of CITED4 in various cancers including breast cancer, colorectal cancer, and lung adenocarcinoma." (PMID 40389954, 2025). "In colorectal cancer, CITED4 silencing leads to G2 cell cycle arrest and disrupts adhesion-related gene expression, affecting tumor invasion." (PMID 40389954, 2025). "In another study, CITED4, a transcriptional cofactor deregulated in colorectal cancer, was knocked down via shRNA-mediation in the colorectal cancer cell line SW480." (PMID 27547510, 2016). "CITED4 is one member of a family of transcriptional cofactors, several of which are deregulated in a variety of tumors, including colorectal cancer (CRC)." (PMID 26243458, 2016).
breast carcinoma (2 papers, 2021 to 2025). "CITED4 is predominantly located in the nucleus; however, cytoplasmic translocation or loss of nuclear expression of CITED4 has been observed in breast cancer development, where it might represent a prognostic marker." (PMID 40389954, 2025). "Hypermethylation of the CITED4 promoter, reduces CITED4 expression in breast cancer, thereby increasing the expression of HIF and its target genes." (PMID 34631530, 2021).
breast tumors (2 papers, 2009 to 2016). "Its family member, CITED4, has been analysed in breast tumours and was found to be associated with HIF1α expression and to be either lost or translocated into the cytoplasm during tumour progression." (PMID 19904269, 2009). "Analysis of CITED4 in a large series of human breast tumors by immunohistochemistry showed both cytoplasmic and nuclear staining, the nuclear staining of CITED4 negatively correlating with HIF-1alpha expression, tumor size and tumor grade." (PMID 26243458, 2016). "However, CITED4 (as well as CITED2) have been shown to bind and inactivate HIF-1alpha, and in breast tumors, a negative correlation exists between CITED4 and HIF-1alpha protein expression, which would apparently contradict a role for HIF-alpha regulation of c-MET in the current study." (PMID 26243458, 2016).
lung adenocarcinoma (2 papers, 2023 to 2025). A carcinoma that arises from the lung and is characterized by the presence of malignant glandular epithelial cells. "For example, CITED4, which was detected to be an SVG by all three methods, has been found to be associated with lung adenocarcinoma." (PMID 37862362, 2023).
pancreatic cancer (2 papers, 2025). "siRNA-mediated knockdown of CITED4 suppresses the invasion and metastasis of pancreatic cancer cells." (PMID 40303346, 2025). "Analyzing the regulatory role of CITED4 in the invasion and metastasis of pancreatic cancer cells through transwell assay and scratch wound healing assay." (PMID 40303346, 2025). "Furthermore, this study identified immune microenvironment alterations during liver metastasis of PDAC and elucidated the interactions between tumor cells and Treg and Tex cells during early dissemination, and the regulatory mechanism by which CITED4 promotes liver metastasis of pancreatic cancer." (PMID 40303346, 2025).
diabetes (1 paper, 2025). "On the other hand, gene expression analysis of mouse embryos exposed to maternal diabetes showed a two-fold increase in Cited4 transcript levels in comparison to wild-type embryos." (PMID 41295244, 2025). "The significance and the importance of diabetes-induced Cited4 transcripts in heart development remain to be established." (PMID 41295244, 2025). "However, diabetes-induced Cited4 expression is unlikely to compensate for the downregulation of Cited2, further indicating that Cited genes have distinct functions." (PMID 41295244, 2025).
Hyperglycemia (1 paper, 2023). An increased concentration of glucose in the blood. "Given the protective role of CITED4 against chronic pathological stresses, such as hyperglycemia and insulin resistance, lower levels of this protein may contribute to increased fibrosis, HW/BW, and decreased cardiac output." (PMID 37237932, 2023).
ischemic heart disease (1 paper, 2025). "Altogether, CITED4 functions as a critical mediator linking exercise-induced cardiomyocyte proliferation with cardioprotection, underscoring its therapeutic potential in ischemic heart disease." (PMID 41295244, 2025).
lung carcinoma (1 paper, 2025). "In lung cancer, CITED4 is induced by heparin-binding epidermal growth factor (HB-EGF) through signal transducer and activator of transcription (STAT3)-dependent pathway, resulting in cell proliferation." (PMID 40389954, 2025).
pancreatic adenocarcinoma (1 paper, 2025). "Multivariate Cox regression analysis of the seven candidate prognostic MDRGs identified CITED4 and CIRBP as independent prognostic factors for both OS and disease-specific survival (DSS) in patients with pancreatic adenocarcinoma." (PMID 40303346, 2025). "To investigate the relationship between CITED4 and the immune microenvironment, we utilized CIBERSORT to calculate immune cell infiltration scores in pancreatic adenocarcinoma patients stratified by high versus low CITED4 expression." (PMID 40303346, 2025).
prediabetes (1 paper, 2018). "Uncovering how context‐specific differential regulation of distinct TZD responses is mediated by Cited4 may open up new possibilities for exploiting and personalizing PPARg modulation in type 2 diabetes or prediabetes." (PMID 29973382, 2018).
prostate carcinoma (1 paper, 2016). A carcinoma that arises from epithelial cells of the prostate gland. "GPR110 has been shown to be overexpressed in lung and prostate cancer and is upregulated in the CITED4-overexpressing cell line." (PMID 26243458, 2016).
tumor (9 papers, 2009 to 2025). "Beyond its role in tumor growth, CITED4 is also a potential biomarker." (PMID 40389954, 2025). "Further, CITED4 knockout (KO) in a highly GEM-resistant cell, PANC-1, significantly suppressed the growth of orthotopically injected tumor cells following GEM treatment, indicating that CITED4 is a potential key regulator of GEM resistance in PC." (PMID 40389954, 2025). "Our results showed that CITED4 and BIRC2 mRNA levels were significantly elevated in tumor tissues compared to normal tissues." (PMID 40389954, 2025).
cancer (5 papers, 2020 to 2025). A tumor composed of atypical neoplastic, often pleomorphic cells that invade other tissues. "Recent studies have suggested that CITED4 plays a crucial role in cancer development and progression." (PMID 40389954, 2025). "From the RNA sequencing data of isolated GEM-resistant PC cells and The Cancer Genome Atlas dataset, 15 GEM resistance-related genes were found to be upregulated, including CITED4, the gene encoding a type of CBP/p300-interacting transactivator implicated in several cancers." (PMID 40389954, 2025). "A canonical cancer pathway involving the NFkB complex is central to this network, which is predicted to activate (denoted by orange relationship lines) various genes upregulated in the dataset, including the transcription regulator CITED4, peptidase ADAMTS9, and kinase PIM3." (PMID 32414099, 2020).
CITED4 also shares sentences with these, for which no sentence is quoted: brain tumors (1 paper); heart failure (1); infarction (1); Insulin resistance (1); Parkinson disease (1); Polydipsia (1); type 2 diabetes (1).